HMGB1 (high mobility group box 1)
Diseases named in the same sentence as HMGB1 in open-access papers (continued):
Sharing a sentence is not in itself a finding about the gene and the disease.
cancer (continued). "Remarkably, OV-mediated cancer cell death is often immunogenic and associated with the expression, release, and/or exposure of DAMPs including ATP, high mobility group box 1 (HMGB1), and calreticulin (CRT)." (PMID 31440242, 2019). "RAGE, a receptor binding to HMGB1, was reportedly associated with invasion capacity in a study using bile duct-cancer cell lines." (PMID 31399104, 2019). "In cancer, HMGB1 can be associated with differentiation of Tregs, recruitment to the TME and enhancement of suppressive features." (PMID 31379812, 2019). "In recent years, HMGB1 has been identified as a key mediator of inflammation- and damage-associated molecular patterns in a variety of inflammatory disorders and cancers." (PMID 30891101, 2019). "Irradiated cancer cells undergo a stressful death that is associated with the release of DAMPs, such as the high-mobility-group Box 1 (HMGB1) alarmin protein, and the upregulation of signals that promote their phagocytosis by DCs, such as calreticulin." (PMID 31221199, 2019). "Dysfunction of intracellular and extracellular HMGB1 has been implicated in the pathogenesis of infections, cancer, neurodegeneration, aging and cardiac disease." (PMID 31331356, 2019). "This is consistent with our results showing that UV irradiation causes HMGB1 release from three different mouse cancer cells lines and soluble factors in the resulting TCL induce DC activation." (PMID 30961656, 2019). "In past, others and we have demonstrated that, naturally occurring or artificially-induced, defects in ecto-CALR exposure, ATP secretion or HMGB1 release can cause cancer cells to resist the pro-immunogenic effects of ICD." (PMID 29707136, 2018). "Meta-analysis revealed no statistical association between rs1045411, rs1360485, rs1412125, or rs2249825 polymorphisms in HMGB1 gene and risk of cancer, either did subgroup analysis of rs1045411 stratified by cancer types and ethnic groups." (PMID 30049847, 2018). "Impaired HMGB1 is associated with the cancer suggesting the potential as a target for cancer therapy." (PMID 29899164, 2018). "Under such condition, large-scale studies, involving haplotype analysis as well as adjustments of potential confounding factors, are required to further elucidate the exact role of HMGB1 and its variants in cancer." (PMID 30049847, 2018). "The association between HMGB1 polymorphism and cancer risks was indicated as odds ratio (OR) along with its related 95% confidence interval (95%CI)." (PMID 30049847, 2018). "We strongly call for further investigations to lift the veil of the underlying mechanisms involved in the relationship between HMGB1 SNPs and cancer risk." (PMID 30049847, 2018). "High level of HMGB1 is always associated with cancer metastasis, suggesting that HMGB1 promotes invasion and metastasis of cancer cells." (PMID 29568761, 2018). "Since its discovery, HMGB1 has been implicated in many disease states including inflammation, immune disorders and cancer." (PMID 28969092, 2017). "In cancer, the dysfunction of HMGB1 has been verified to be associated with all the central hallmarks of cancer." (PMID 28969092, 2017). "Clinically, the overexpression of HMGB1 has been significantly associated with a poor survival rate in various cancers." (PMID 28727734, 2017). "Dysfunction of intracellular and extracellular HMGB1 has been implicated in multiple human diseases or diverse pathologies including infections, cancer, neurodegeneration, aging, and heart disease." (PMID 28374746, 2017). "Altered expression of HMGB1 has been implicated in a wide range of pathological processes, including inflammation and cancer." (PMID 28423715, 2017). "Recent clinical studies have shown that HMGB1 is a potential diagnostic or prognostic biomarker in a variety of inflammatory disorders and cancers." (PMID 28348451, 2017).
cancer (continued). "The results from this work have shown that HMGB1, a histone-associated nuclear protein normally involved in DNA stabilisation, is actively released from cancer cells in response to low-glucose levels." (PMID 26979829, 2016). "We also found an indication by microarray analysis and meta-analysis that HMGB1 expression was associated with the cancer TNM Staging System." (PMID 26840258, 2016). "Treatment with the TLR4 ligands LPS and LPS + HMGB1 also caused significantly increased cancer cell proliferation compared to untreated cells (MIAPaCa-2: 127%, p < 0.05 and 132%, p < 0.05; BxPC-3: 118% and 148%, p < 0.0001; PaCaDD135: 104% and 112%, p < 0.05)." (PMID 27941651, 2016). "The results indicated that HMGB1 overexpression was associated with poorer prognosis in patients with various types of cancer." (PMID 27391431, 2016). "HMGB1 is a nuclear protein, which is released from damaged or necrotic cells and associated with inflammatory diseases and cancer." (PMID 27026438, 2016). "HMGB1 is also a protein implicated in cancer malignant development by stimulating migration and enhancing proliferation." (PMID 26899177, 2016). "HMGB1 overexpression was significantly associated with a poorer OS in patients with cancer (HR: 1.99; 95% CI, 1.71-2.31)." (PMID 27391431, 2016). "The underlying mechanisms involved in the relationship between HMGB1 expression and prognosis in patients with cancer are uncertain." (PMID 27391431, 2016). "HMGB1 has been previously implicated in CRC with controversial roles in cancer immunity and metastasis." (PMID 26388988, 2015). "Being a DNA-modulating chaperone, HMGB1 can influence genome instability and mutation, another hallmark of cancer." (PMID 26854151, 2015). "In summary, the findings of these clinical studies underline the relevance of circulating HMGB1 and sRAGE for staging, therapy monitoring and prediction in diverse cancer settings." (PMID 26854151, 2015). "HMGB1 overexpression is associated with hallmarks of cancer, including unlimited replicative potential, vasculogenesis, evasion of apoptosis and insensitivity to growth inhibitors." (PMID 25652880, 2015). "Recent findings indicate that HMGB1 dysfunction is associated with every hallmark of cancer and contributes to cancer initiation and development." (PMID 25356587, 2014). "Cancer-associated fibroblasts and high mobility group box 1 (HMGB1) protein have been suggested to mediate cancer progression and chemotherapy resistance." (PMID 25512109, 2014). "Accumulated evidences indicate that HMGB1 is associated with ten functional capabilities of cancers as Hanahan and Weinberg described in 2011." (PMID 25356587, 2014). "Overexpression of HMGB1 is associated with six hallmarks of cancer, including self-sufficiency in growth signals and insensitivity to inhibitors of growth." (PMID 24996221, 2014). "Over-expression of HMGB1 is associated with each of the hallmarks of cancer including unlimited replicative potential, angiogenesis, evasion of apoptosis, self-sufficiency in growth signals, and insensitivity to inhibitors of growth." (PMID 24455688, 2013). "Several reports indicated that the serum HMGB1 level was elevated in patients with various types of cancer and its diagnostic values were evaluated in some tumors." (PMID 22496788, 2012). "HMGB1 expressed and secreted by cancer cells are associated with increased metastasis and poorer outcomes in a wide variety of tumors." (PMID 20579387, 2010). "Since loss of HMGB1 in cancer cells leads to impaired DNA repair in vitro and in vivo, it has been suggested that HMGB1 deficiency may increase sensitivity to alkylating agents or ionizing radiation." (PMID 40804938, 2025). "High mobility group box 1 (HMGB1) is linked to cancer’s telltale signs." (PMID 41151762, 2025).
cancer (continued). "Because HMGB1-deficient cancers may have limited capacity to recruit inflammatory cells through secretion of HMGB1, it was speculated that TLR4 agonists may be able to substitute HMGB1 in its role of activating T cells by binding to TLR4." (PMID 40804938, 2025). "In addition, the underlying mechanistic relationships between HMGB1, cancer metastasis, and drug resistance warrant further investigation, either through molecular signaling or concept confirmation in animal models." (PMID 40331953, 2025). "Both increased and reduced levels of HMGB1 in cancer cells have been found to be linked to aggressive cancer phenotype, and it was proposed that these different roles may depend on the tissue/cell types involved." (PMID 40804938, 2025). "HMGB1 has also been implicated in different diseases, including cancer." (PMID 38725632, 2024). "HMGB1 is the best studied member of the family exhibiting a variety of functions and being implicated in several immune, metabolic, and inflammatory diseases, including cancer." (PMID 37511951, 2023). "In summary, this study investigated the role of HMGB1 in KS, a cancer caused by KSHV infection." (PMID 37520371, 2023). "In cancer, HMGB1 is frequently overexpressed and is associated with poor patient prognosis." (PMID 37520371, 2023). "The outcomes indicated that HMGB1 expression levels were significantly associated with the clinical stage of the following cancer types: Adrenocortical carcinoma (ACC) (p‐value = 0.0239), LIHC (p‐value = 0.0209), SKCM (p‐value = 0.0133) and THCA (p‐value = 0.0348) but not others." (PMID 35765707, 2022). "High-mobility group box 1 (HMGB1) is acknowledged as a proinflammatory cytokine that creates a chronic inflammation microenvironment, contributing to the development of inflammation-associated cancers, including epithelial malignancies." (PMID 35462765, 2022). "Although targeting HMGB1 may contribute to overcoming metastasis and recurrence of cancer, there are few reports about the association between HMGB1 and CSCs." (PMID 35637945, 2022). "Therefore, the inhibitory mechanisms of C6 on the HMGB1-RAGE-ERK1/2 axis are considered to cause the suppression of not only inflammation response but also cancer cell proliferation, thus inducing apoptosis." (PMID 35408786, 2022). "Moreover, oncolytic viruses have the ability to promote adaptive and innate immune responses upon infection and killing of cancer cells, e.g., mediated by the release of danger-associated molecular patterns (DAMPs) like high mobility group box 1 (HMGB1)." (PMID 34135475, 2022). "In the cytoplasm, HMGB1 is mainly associated with the regulation of autophagy in cancer cells." (PMID 35637945, 2022). "The present studies suggested that Nal-P-113 and Dip-P-113 might cause cancer cells to undergo the necrosis pathway, and HMGB1 protein can be detected as early as 2 h post-treatment." (PMID 35625834, 2022). "To assess whether the loss of the C-terminal region of HMGB1 might impact the ability of the full-length protein to impair aerobic respiration in cancer cells, we tested the effects of both forms of HMGB1 on cellular bioenergetics." (PMID 35887213, 2022). "Aberrant HMGB1 signaling is associated with various human carcinomas." (PMID 34617194, 2022). "Currently, the molecular mechanisms underlying the role of the immunogenic form of HMGB1 in determining the capability of human cancer cells to escape host immune surveillance remain unclear." (PMID 34234778, 2021). "For example, the loss of HMGB1/2 from the nucleus results in the reorganization of genome architecture, which has direct implications for gene expression and ultimately the progression of cancers, cardiovascular diseases, and parasitic immune evasion." (PMID 34680084, 2021).
cancer (continued). "The pooled results demonstrated that HMGB1 rs1045411 polymorphism emerge as a risk factor for cancer, as a significant association between increased cancer risk and TT genotype was indicated in the comparison of the TT vs. CC+TC genotype (OR=1.35; 95% CI: 1.09-1.67; p=0.005)." (PMID 33628090, 2021). "Notwithstanding the importance of the acquisition of definitive insights into the origins, regulation of chemical modification and biological functions of HMGB1 variant molecules, several other key areas of the role of HMGB1 in cancer also necessitate clarification." (PMID 32664328, 2020). "After exposure to ICD inducers, the secretion of damage-associated molecular patterns (DAMPs) by cancer cells with the release of high mobility group box 1 (HMGB1), adenosine triphosphate (ATP) expression, and surface exposure of calreticulin (CRT) mainly contribute to the induction of ICD." (PMID 34138119, 2020). "High mobility group box 1 (HMGB1) is associated with the hallmarks of cancer." (PMID 32322202, 2020). "Indeed, the diagnostic accuracy of HMGB1 for stage I cancer was significantly higher than that of carcinoembryonic antigen (CEA)." (PMID 30755156, 2019). "As a consequence, we found cancer stem cell-associated proteins, such as mmp2, mmp9, mmp13, mmp14, paxillin, Ras, src and c-myc, as well as genes expressed in the immune system, such as C5, C9, and HMGB1." (PMID 31832023, 2019). "Cancer-associated fibroblasts derived HMGB1 promoted stemness and tumourigenicity in breast cancer." (PMID 31558702, 2019). "Hence, we conducted a comprehensive study based on current research to better understand the association between HMGB1 gene polymorphisms and cancer risks." (PMID 30049847, 2018). "Thus it is intriguing that HMGB1 has been linked to the IL-8 pathway in an immunologically relevant manner in the context of cancer." (PMID 29464075, 2018). "Finally, overexpression of HMGB1 is reported to be associated with adverse prognosis in cancer patients." (PMID 30292233, 2018). "Many studies have reported that HMGB1 is associated with cancer cell migration and invasion." (PMID 29850505, 2018). "Our results revealed no statistical association between current four polymorphism loci and cancer risks, suggesting that the attempt of applying HMGB1 variants as a therapeutic target or a prognosis predictor might still require a second thought." (PMID 30049847, 2018). "However, HMGB1 is deemed to play pleiotropic roles in cancers, we strongly call for large-scale studies with high evidence level to uncover the exact relationship between HMGB1 gene variants and cancer progression." (PMID 30049847, 2018). "HMGB1 is expressed in various cancers and is associated with cancer progression." (PMID 30643519, 2018). "The aim of the present study was to determine whether High mobility group box 1 (HMGB1) polymorphism was associated with cancer susceptibility." (PMID 30049847, 2018). "Since rs1045411 polymorphism was closely correlated with an altered binding of miR-505-5P in the 3′-UTR of mRNA transcripts, HMGB1 gene polymorphisms could emerge as a crucial player in cancer development through a post-transcriptional mechanism." (PMID 30049847, 2018). "Elevated HMGB1 levels are associated with poor survival of cancer patients." (PMID 29728635, 2018). "Loss of HMGB1 increases DNA damage and sensitizes cancer cells to radiation." (PMID 28642840, 2017). "Indeed, cancer cell irradiation generates damage-associated molecule patterns (DAMPs), such as high mobility group box 1 (HMGB1)." (PMID 28769933, 2017). "Based on the association between autophagy and apoptosis in cancer cells, HMGB1 may be an important therapeutic target in cancer treatment." (PMID 28771183, 2017). "Thus, secreted HMGB1 can kill cancer cells by causing a brisk metabolic shift restricting their energy supply to glycolysis." (PMID 26948869, 2016). "Therefore, serum HMGB1 can be a potential powerful diagnostic and prognostic biomarker for patients with cancer." (PMID 27391431, 2016).
cancer (continued). "Therefore, we performed a literature-based systematic review and meta-analysis in order to assess the association of HMGB1 expression with prognosis in patients with cancer." (PMID 27391431, 2016). "In these 17 studies, HMGB1 was respectively detected using immunohistochemistry (IHC) staining and qRT-PCR in cancer tissues by 11 and 2 researches, and the remaining 4 investigations evaluated the expression of serum HMGB1 using enzyme-linked immunosorbent assay (ELISA)." (PMID 27391431, 2016). "We aim to assess the association of HMGB1 expression with prognosis in cancer patients." (PMID 27391431, 2016). "HMGB1 overexpression is associated with poorer prognosis in patients with various types of cancer, suggesting that it is a prognostic factor and potential biomarker for survival in cancer." (PMID 27391431, 2016). "Given the crucial role of HMGB1 in the development and progression of cancer, it is plausible that the polymorphisms of HMGB1 may affect the clinical outcomes of GC." (PMID 27116470, 2016). "Through these actions, HMGB1 has been implicated in the pathogenesis of various clinical conditions, including sepsis, ischemia-reperfusion, meningitis, neurodegeneration, aging, and cancer." (PMID 25622595, 2015). "Evidence suggests that HMGB1 may induce autophagy in cancers associated with increased sensitivity to cytotoxic anticancer agents." (PMID 25652880, 2015). "In the pathophysiology of cancer, increased expression of HMGB1 and RAGE is associated with proliferative activity and metastatic potential in many types of tumors, including breast cancer, hepatocellular carcinoma, melanoma, glioma, prostate cancer, gastric cancer, and colorectal cancer." (PMID 25622595, 2015). "Furthermore, HMGB1 has been implicated in many hallmarks of cancer, including apoptosis, angiogenesis, invasion, metastasis and inflammatory microenvironment." (PMID 26239046, 2015). "Various clinical studies indicate that monitoring parameters linked to HMGB1 release and signaling may convey prognostic or predictive information for cancer patients." (PMID 26300886, 2015). "Targeting cancer-associated fibroblasts which have more genetic stability than cancer cells is an alternative therapeutic approach to interrupt the cycle of fibroblast-induced HMGB1 in mediating acquired chemoresistance." (PMID 25512109, 2014). "Hmgb1, a highly conserved nuclear protein, served as an early mediator of inflammation and cell injury and plays a key role in many pathogenic states including cancers." (PMID 24453427, 2013). "Of note, HMGB1 expression has already been associated with various cancer diseases." (PMID 23372777, 2013). "Over-expression of HMGB1 is associated with the hallmark of cancer such as unlimited potential for replication, angiogenesis, apoptosis, self-sufficiency in growth signals, insensitivity to antigrowth signals, inflammatory microenvironment, tissue invasion, and metastasis." (PMID 23617783, 2013). "The association of HMGB1 overexpression and poor prognosis has been reported in cancer patients." (PMID 22496788, 2012). "Moreover, the diagnostic accuracy of HMGB1 for stage I cancer was significantly higher than that of CEA (sensitivity: 41.2% vs. 5.9%; specificity: 96% vs. 90.7)." (PMID 22496788, 2012). "Recently, HMGB1 is known to be also released during autophagy and late apoptosis; for instance, anticancer agents that enhance autophagy and apoptosis cause HMGB1 release in cancer cells." (PMID 21917150, 2011). "In cancer, overexpression of HMGB1 is associated with the hallmarks of cancer, including sustained proliferative potential and replicative immortality, angiogenesis, apoptosis resistance, self-sufficient growth, insensitivity to suppressors of growth, inflammation, and invasion and metastasis." (PMID 21917150, 2011).